SLC7A11 (solute carrier family 7 member 11)
Diseases named in the same sentence as SLC7A11 in open-access papers (continued):
Sharing a sentence is not in itself a finding about the gene and the disease.
tumor (continued). "Recent studies have demonstrated that SLC7A11 is markedly upregulated in OS cells and tissues, where it enhances glutathione (GSH) synthesis and protects tumor cells against intracellular oxidative stress." (PMID 41343099, 2025). "Targeting the CSC/EMT antigen Cripto-1 (Cr-1) in the 4T1 model or the xCT protein, also known as SLC7A11, in the 4T1 or TUBO models with a plasmid-based vaccine inhibited tumor growth by about 30–40% and significantly reduced metastatic spread to the lungs." (PMID 40432134, 2025). "IFN-γ released from CD8+ T cells downregulates the expression of SLC7A11/SLC3A2 by activating the JAK/STAT pathway, which promotes tumor ferroptosis, contributing to the antitumor efficacy of immunotherapy." (PMID 41373022, 2025). "Utilizing mouse tumor models, we conducted an in-depth evaluation of the ferroptosis status and the expression changes of CAV1 and SLC7A11 at the single-cell level within tumor tissues." (PMID 40180904, 2025). "Activated CTLs secrete IFN-γ, which downregulates tumor SLC7A11 and SLC3A2 (components of system Xc−), thereby sensitizing tumor cells to ferroptosis." (PMID 41301464, 2025). "Consistently, we also found the colocalization of WTX-L with SLC7A11 and FTL, suggesting that WTX as a regulator of ferroptosis is prevalent in tumor development." (PMID 40109379, 2025). "High SLC7A11 expression promotes GSH synthesis by mediating cystine transport, upregulating GPX4 activity, enhancing the antioxidant capacity of tumor cells, scavenging ROS, and inhibiting ferroptosiss." (PMID 40084254, 2025). "At the same time, Honokiol can reduce the expression of key antioxidant factors SLC7A11 and GPX4, further weakening the antioxidant capacity of tumor cells." (PMID 40539051, 2025). "The upregulation of solute carrier family 7 member 11 (SLC7A11), a cystine glutamate transporter, partially facilitates tumor progression by suppressing ferroptosis." (PMID 40936722, 2025). "WB and IHC analysis of subcutaneous tumor tissues in the CDX and PDX models showed that TMEM160 knockdown reduced the expression of NRF2 and its target genes, GPX4 and SLC7A11." (PMID 40223081, 2025). "The results revealed that the expression of SLC7A11 and SLC3A2 was significantly lower in tumor tissues with higher IFN-γ expression in the HRNE group." (PMID 40837737, 2025). "In this mechanism, the increased levels of IFN-γ secreted from activated CD8+ T cells could suppress SLC3A2 and SLC7A11 (two important subunits of the glutamate-cystine antiporter system xc-) and restrain tumor cell cystine uptake, thus leading to lipid peroxidation and ferroptosis in tumor cells." (PMID 40539046, 2025). "In accordance with cell experiment results, lower protein levels of GPX4, p-Stat3, Stat3, SLC7A11 and SLC3A2 were found in nude mice tumor tissues from UA (40 mg/kg) group." (PMID 41341590, 2025). "In summary, our study demonstrates that Huaier effectively induces ferroptosis in NSCLC by simultaneously modulating the SLC7A11/GPX4 axis and ferritinophagy, thereby exerting its anti-tumor effects both in vitro and in vivo." (PMID 40623982, 2025). "Western blot analysis showed that sh-circASH1L accelerated the cisplatin-induced reduction of GPX4 and SLC7A11 expression, as well as the downregulation of CDCA7 and RRM2 in tumor tissues." (PMID 40630134, 2025).
tumor (continued). "Future studies are needed to confirm that the tumor-suppressive effect of PTBP1 depletion in EC is, at least partially, dependent on SLC7A11 downregulation." (PMID 41313521, 2025). "Similarly, pharmacological inhibition of SLC7A11 through extracellular cysteine depletion mediated by cyst(e)inase or the use of the erastin analogue imidazole ketone erastin has been demonstrated to induce ferroptosis and/or inhibit tumour growth in preclinical models." (PMID 39354653, 2025). "The combined inhibition of SLC7A11 and NQO1 had a more significant suppressive effect on tumor growth in the subcutaneous HCC model." (PMID 40007539, 2025). "Another important gene in disulfidptosis, SLC7A11 was found to be overexpressed in various cancer types, including HCC, and plays a role in tumor promotion." (PMID 40362690, 2025). "Curcumin, neferine, and TDH have all been demonstrated to reduce GPX4 or SLC7A11 activity, increase ROS, and suppress ATC tumor growth in vivo." (PMID 41294853, 2025). "Similar to the in vitro experiments, the expression of Nrf1/2, HO‐1, SLC7A11 and TFR in HepG2 xenograft tumours was significantly increased after SSPH I treatment." (PMID 40394754, 2025). "Moreover, different SLC7A11 inhibitors may synergistically suppress tumor progression." (PMID 39569390, 2025). "Increasing evidence indicates that tumor cells can upregulate SLC7A11 and GPX4 to protect cells from radiotherapy-induced ferroptosis, suggesting ferroptosis is crucial to tumor radiosensitivity." (PMID 40084254, 2025). "In vivo, the combination of NaBu and erastin significantly reduces tumor growth and increases lipid peroxidation, with the antitumor effect attributed to ATF3-mediated downregulation of SLC7A11." (PMID 41301848, 2025). "Immunohistochemistry analysis revealed that Sorafenib treatment significantly reduced the levels of SLC7A11 and Ki67, a proliferation marker, and increased the level of 4-HNE, a marker of ferroptosis, in tumor tissues." (PMID 39833180, 2025). "OSCC cells exhibit heightened reliance on anti-ferroptotic defenses such as GPX4, SLC7A11, FSP1, and Nrf2, and disrupting these pathways suppresses tumor growth and restores sensitivity to chemotherapy, radiotherapy, and immunotherapy." (PMID 41227330, 2025). "Promoters of some genes with functions in amino acid transport (Slc7a11, Slc38a1, and Slc43a1) were occupied by ATF4 in DLD-1 MycER tumor cells." (PMID 40542844, 2025). "A subcutaneous tumor model was established using HCCLM3 cells in nude mice to investigate the impact of NQO1 and SLC7A11 on tumor growth." (PMID 40007539, 2025). "Although curcumin has been reported to induce ferroptosis in various cancer types, its core signaling axis, such as the inhibition of SLC7A11/GPX4, exhibits significant variations across different tumor types." (PMID 41515171, 2025). "Inhibition of SLC7A11 resulted in cessation of GSH synthesis and targeted cell death in KRAS-mutant cancer cells, leading to the prevention of tumor development in in vivo models." (PMID 40403492, 2025). "Combining NSC48160 with the SLC7A11 inhibitor HG106 synergistically eliminated HCC cells in vitro and suppressed tumor growth in vivo." (PMID 40390765, 2025).
tumor (continued). "Interferon-gamma (IFN-γ) regulates the expression of SLC3A2, SLC7A11, and ACSL4, subsequently inducing immunogenic ferroptosis in tumor cells." (PMID 40260246, 2025). "This overreliance creates a targetable vulnerability; silencing SLC7A11 sensitizes OSCC cells to ferroptosis and impairs tumor growth." (PMID 41227330, 2025). "Immunohistochemistry analysis revealed that IKE treatment resulted in significant reductions in SLC7A11 and Ki67 levels, as well as increases in 4-HNE levels in tumor tissues." (PMID 39833180, 2025). "The expression levels of the SLC7A11 gene in HNSCC tissues were analyzed using the UALCAN database based on cancer stage, tumor grade, and HPV status." (PMID 40378782, 2025). "Gaining a deeper understanding of SLC7A11’s dual role in these cell death processes could lead to innovative strategies for influencing cell fate in various diseases, particularly in the cancer treatment, where the ability to evade cell death is a key feature of tumor progression." (PMID 40535572, 2025). "HOXB9, a potential transcriptional regulator of SLC7A11, was upregulated in NSCLC tissues and functions as a tumor promoter in cancer progression." (PMID 40427734, 2025). "IFNγ operates through a cysteine/glutamic acid reverse transport system, solute carrier family 7 member 11(SLC7A11) and SLC3A2, that targets the surface of tumor cell membranes." (PMID 39820341, 2025). "SLC7A11 was found to be overexpressed in various cancer types, including HCC, and plays a role in tumor promotion." (PMID 40362690, 2025). "Beyond regulating GCL, NRF2 also induces SLC7A11 (xCT) and GPX4, strengthening cellular defenses against ferroptosis and allowing tumor cells to evade iron-dependent cell death." (PMID 41333220, 2025). "Sh‐YTHDF2 and DNase I inhibited GPX4, SLC7A11, and FTH1 expression in the tumour, while increasing ACSL4 and PTGS2 levels and had a superimposed effect." (PMID 39865544, 2025). "Thus, we propose that SLC7A11 may be a potential tumor-promoting gene in HCC." (PMID 40978058, 2025). "Recent studies have shown that IFN-γ can downregulate SLC3A2 and SLC7A11 while upregulating ACSL4, promoting tumor cell ferroptosis." (PMID 38965216, 2024). "The tumor-suppressor activity of BAP1 is mediated, in part, by the repression of SLC7A11 expression through deubiquitinating of H2A on the SLC7A11 promote." (PMID 38267442, 2024). "Mechanistically, high levels of SLC7A11 expression, H2O2 therapy, and cystine uptake in tumor cells trigger the accumulation of harmful disulfide molecules and NADPH depletion, eventually resulting in rapid cell death—disulfidptosis." (PMID 38185671, 2024). "IL6 can reverse the SLC7A11 knockout effect through the JAK2/STAT3 pathway, inhibit ferroptosis and promote tumor resistance." (PMID 39544949, 2024). "Studies have shown that the anti-tumor effect of BAP1 is partly due to the ubiquitination of H2A on the promoter of SLC7A11, thus inhibiting the expression of SLC7A11 and inducing ferroptosis." (PMID 38475936, 2024). "This disruption of the SLC7A11-GSH-GPX4 pathway and iron metabolism substantially encourages ferroptosis within tumor cells, evidenced both in vitro and in vivo." (PMID 38505601, 2024). "As core effector cells in antitumor immunity, CD8+ T cells enhance tumor cell lysis by secreting interferon-γ (IFN-γ), which inhibits the expression of SLC7A11 and SLC3A2—subunits of the system Xc– in tumor cells." (PMID 39850905, 2024).
tumor (continued). "IFNγ enhances ferroptosis under erastin or RSL3 treatment by promoting STAT1 binding to the SLC7A11 promoter, depleting GSH, and increasing lipid peroxidation in tumor cells." (PMID 39595619, 2024). "Specifically, LRP1B impacted the survival of tumor cells by modulating the phosphorylation level of the transcription factor STAT3, and consequently regulating the expression of SLC7A11." (PMID 39660409, 2024). "Research shows that immunotherapy-activated CD8+ T cells can enhance ferroptosis-specific lipid peroxidation in tumor cells by downregulating the expression of SLC3A2 and SLC7A11, via the release of IFN-γ." (PMID 38475936, 2024). "The upregulation of the SLC7A11/GSH/GPX4 axis, a key ferroptosis defense system, is a significant evasion mechanism evolved by tumor cells." (PMID 38453898, 2024). "Meanwhile, protein levels of GAS41 declined in line with significantly decreased protein levels of SLC7A11 and GCLC, suggesting that GAS41-mediated antioxidant regulators expression is critical for tumor growth in vivo." (PMID 38514704, 2024). "Our findings show that FTO, SLC7A11, and GPX4 protein are also highly expressed in patient tumor tissues than in normal tissues, respectively." (PMID 38600610, 2024). "For example, CD8+ T cells suppress the expression of SLC7A11 and SLC3A2 in tumor cells via IFNγ release, increasing tumor cell sensitivity to ferroptosis." (PMID 39273090, 2024). "Immunohistochemistry for SLC7A11, SLC3A2, and PD-L1 will be performed on tumor tissues from ISMC patients to preliminarily explore potential therapeutic targets for ISMC." (PMID 39807126, 2024). "Mupirocin significantly decreased the tumor growth, tumor masses, Ki67 expression, GPX4, and SLC7A11 levels, as well as induced the expression of ferroptosis biomarker 4HNE." (PMID 38600610, 2024). "The function of SLC7A11 in the process of ferroptosis is well-established, as it regulates the synthesis of glutathione (GSH), thereby influencing tumor development along with drug resistance in non-small cell lung cancer (NSCLC)." (PMID 38241838, 2024). "Tumor tissues of the CK treatment group showed inhibited GPX4 and SLC7A11 expression and down-regulated p-FOXO1." (PMID 38664638, 2024). "And retrospective analysis showed that the expression of SLC7A11 was negatively correlated with CD8+ T cell signaling, INF-γ level and prognosis of tumor patients." (PMID 39040097, 2024). "Another study showed that XK-81, a metabolite of Leathesia nana (Chordariaceae), decreased SLC7A11 and GPX4 expression and induced ferroptosis in tumor tissues." (PMID 38292937, 2024). "Overexpression of LRP1B increased the expression of SLC7A11 and inhibited the increase of lipid ROS and MDA induced by Erastin in tumor cells." (PMID 39660409, 2024). "In the tumor microenvironment, TNFγ downregulates SLC7A11 to activate CD8+ T cell ferroptosis, which facilitates T cell exhaustion and thus contributes to tumor cell survival." (PMID 39309434, 2024). "This is due to the ability of IFN-γ to activate the JAK-STAT1 signaling pathway in tumor cells, enhance the binding of STAT1 to the SLC7A11 transcription start site, and down-regulate the expression of Xc- system." (PMID 39359721, 2024). "The expression of SLC7A11, SLC3A2, RPN1 and NCKAP1 were found to be upregulated in the tumor tissues compared with that in the corresponding normal tissues from the TCGA data." (PMID 38528532, 2024). "Solute Carrier Family 7 member 11 (SLC7A11) is a crucial gene involved in disulfidoptosis and plays a key role in tumor development and progression." (PMID 38862242, 2024).
tumor (continued). "Western blot results in tumor tissues showed that erastin can increase the expression of SOCS2, but inhibit SLC7A11 and GPX4 expression, which can be further promoted by POU6F1 or lncRNA-CASC2 overexpression." (PMID 38267746, 2024). "For the subcutaneous xenograft model, combined treatment with POLQ inhibitors and sulfasalazine, a ferroptosis inducer that inhibits SLC7A11, synergistically suppressed MGC-803 xenograft tumor growth." (PMID 38575587, 2024). "Targeting GPX4, SLC7A11 or FSP1, which have all been reported to be upregulated in NSCLC, has been shown to reduce tumor growth in different NSCLC model systems." (PMID 38908072, 2024). "On the other hand, immune checkpoint inhibitors, for instance anti-PD-1 and anti-PD-L1, can suppress the expression level of SLC7A11 and GPX4 on tumors, activate CD8+ T cells in tumor microenvironment, and enhance the release of IFN-γ." (PMID 38323315, 2024). "The reduced hypoxia leads to lower HIF‐1α levels, decreasing SLC7A11 subunit activity, impeding GSH synthesis, and reducing tumor cell resistance to ferroptosis." (PMID 38867396, 2024). "In 50 paired tumors and adjacent non-tumor tissues from TCGA COREAD database, 27 of 50 (54 %) CRC samples showed upregulation of SLC1A4, SLC1A5, SLC7A11 and SLC3A2 simultaneously, and 17 of 50 (34 %) CRC samples showed upregulation of three transporter genes." (PMID 39079386, 2024). "The SLC7A11-associated high-rate cysteine metabolism in tumor cells relies on the pentose phosphate pathway to generate substantial amounts of NAPDH, establishing a link to metabolic vulnerabilities that could guide therapies targeting cancers with high SLC7A11 expression." (PMID 38831301, 2024). "xCT (system Xc‐), also known as solute carrier Family 7 Member 11 (SLC7A11), has attracted considerable interest in understanding tumor biology and therapeutic targeting." (PMID 39487701, 2024). "SLC7A11 is overexpressed in a variety of human cancers and induces GSH synthesis by promoting Cys uptake and Glu release, thereby promoting tumor survival." (PMID 39400975, 2024). "Here, we found that inhibiting PPARγ in OSCC can promote ferroptosis by upregulating HMOX1 and promoting disulfidptosis through the upregulation of SLC7A11 and the subsequent recruitment of additional cDCs and CD8+ T cells to inhibit tumor development." (PMID 38786003, 2024). "When we overexpressed SLC7A11 in LRP1B knockdown cell lines, we rescued tumor cells from erastin‐induced ferroptosis, whereas knocking down SLC7A11 in LRP1B knockdown cell lines restored the sensitivity of tumor cells to erastin‐induced ferroptosis." (PMID 39660409, 2024). "Meanwhile, the stability and expression of SLC7A11 is affected by OUTB1 and BAP1 to promote or inhibit tumor ferroptosis." (PMID 38575922, 2024). "This study highlights the crucial role of CPT1A-mediated MDSC ferroptosis resistance through SLC7A11 metabolic reprogramming and MDSCs’ immunosuppressive function via the ARG1 signaling pathway in persisting tumor immune evasion." (PMID 39596904, 2024). "Reducing LRP1B expression resulted in decreased SLC7A11 expression, as well as elevated levels of Lipid ROS and MDA induced by erastin in tumor cells." (PMID 39660409, 2024). "As given that knockdown FTO enhances the anti-tumor effects of Erastin and RSL3, which targets SLC7A11 and GPX4, respectively." (PMID 38600610, 2024). "Based on these data, it can be concluded that HCP5‐132aa primarily inhibits ferroptosis by regulating the expression of SLC7A11 and G6PD, thereby promoting malignant proliferation and tumor progression in GC." (PMID 39447131, 2024). "An important finding in this context is that the inhibition of SLC7A11, mediated by CD8+ T-cells, triggers ferroptosis and thus cell death of the tumor cells." (PMID 39062119, 2024). "For example, CD8 + T cells in the TME promote ferroptosis in tumor cells by releasing interferon-γ (IFN-γ) to reduce SLC3A2 and SLC7A11 expression levels." (PMID 38816377, 2024).